HSPA8 (heat shock protein family A (Hsp70) member 8)
Diseases named in the same sentence as HSPA8 in open-access papers (continued):
Sharing a sentence is not in itself a finding about the gene and the disease.
autism (1 paper, 2016). Persistent deficits in social interaction and communication and interaction as well as a markedly restricted repertoire of activity and interest as well as repetitive patterns of behavior. "GABPA was recently found to bind human-specific binding sites and regulate gene expression of at least four genes (ALDOA, HSPA8, TP73, and TMBIM6) that have been associated with cognitive diseases such as autism, AZ, PD and other brain disorders." (PMID 27014338, 2016).
autoimmune hepatitis (1 paper, 2015). Hepatitis caused by autoantibodies. "Anti-HSPA8 AAbs are implicated in the pathogenesis of both cancer-associated retinopathy (CAR) and autoimmune hepatitis." (PMID 26717306, 2015).
breast tumor (1 paper, 2022). "We therefore next examined the co-expression correlation between HSPs and co-chaperones including HSP90 family (HSP90AA1, HSP90AB1), HSP70 family (HSPA1A, HSPA1B, HSPA8) and BAG family (BAG1, BAG2, BAG3) among 960 breast tumor samples registered in the Cancer Genome Atlas (TCGA)." (PMID 36114410, 2022).
carotid atherosclerosis (1 paper, 2022). A thickening and loss of elasticity of the walls of carotid arteries that occur with formation of atherosclerotic plaques. "In conclusion, the HSPA8 SNP (rs2236659) is associated with carotid atherosclerosis in NAFLD in men." (PMID 35886046, 2022).
dry eye (1 paper, 2022). "Additionally, the expression of both YWHAZ and HSPA8 has been shown to negatively correlate with fluorescein tear break-up time (FTBUT), suggesting these proteins may play a role in dry eye symptoms." (PMID 35216421, 2022).
endometrial tumor (1 paper, 2022). "Previous studies have shown that HSPA8 gene knockout can significantly inhibit the proliferation and promote the apoptosis of endometrial tumor cells." (PMID 36452344, 2022).
glaucoma (1 paper, 2023). Increased pressure in the eyeball due to obstruction of the outflow of aqueous humor. "Next, the GWAS analysis was conducted to confirm that the pathogenic regions of HSPA8 and RPL15 in glaucoma were located on chromosome 11 and 3, respectively, and significant SNPs corresponding to 2 hub genes were found." (PMID 37968618, 2023). "However, in this study, it was found that the expression of Hspa8 was up-regulated in the rat COH glaucoma model that was induced by episcleral vein cauterization, compared with the normal control group, which confirmed the results of bioinformatics analysis of POAG to some extent." (PMID 37968618, 2023). "The expression levels of hub genes were significantly correlated with the expression levels of multiple glaucoma-related genes, among which HSPA8 was significantly negatively correlated with CYP1B1 (Pearson r = − 0.48) and RPL15 was significantly positively correlated with WDR36 (Pearson r = 0.58)." (PMID 37968618, 2023).
gout (1 paper, 2022). A condition characterized by painful swelling of the joints, which is caused by deposition of urate crystals. "Candidate targets of turmeric for gout were HSPA8, VCP, HSP90AB1, HSPA5, HSPA1B, NFKB1, and STUB1." (PMID 36276864, 2022).
head and neck squamous cell carcinoma (1 paper, 2022). A squamous cell carcinoma that arises from any of the following anatomic sites: lip and oral cavity, nasal cavity, paranasal sinuses, pharynx, larynx, and salivary glands. "In a variety of cancers, including BRCA and head and neck squamous cell carcinoma, the expression of HSPA8 mRNA in tumor tissues was significantly higher than that in normal tissues." (PMID 36452344, 2022).
heart failure (1 paper, 2020). Inability of the heart to pump blood at an adequate rate to meet tissue metabolic requirements. "Underexpression of HSPA8 and HSPA9 will disrupt cardiomyocyte homeostasis and interfere with critical cellular functions by small aggregates of proteins, which finally contributes to heart failure and hereditary heart diseases." (PMID 32595699, 2020).
Hepatic steatosis (1 paper, 2022). Steatosis is a term used to denote lipid accumulation within hepatocytes. "Compensatory activation of macrolipophagy, which is independent of HSC70, might cause similar severity of hepatic steatosis between the HSPA8 genotypes." (PMID 35886046, 2022).
HIV-1 infection (1 paper, 2023). The type species of lentivirus and the etiologic agent of acquired immunodeficiency syndrome (AIDS). "For example, although HSPA8 has been shown to play an important role in replication and assembly of other viruses, its role in HIV-1 infection remains unclear." (PMID 36845091, 2023).
intervertebral disc degeneration (1 paper, 2025). "Further mechanistic studies have revealed that UCHL1 regulates HSPA8 through deubiquitination, thereby activating the chaperone-mediated autophagy pathway, which plays a critical protective role in delaying intervertebral disc degeneration." (PMID 41346614, 2025).
ischemia reperfusion injury (1 paper, 2022). Adverse functional, metabolic, or structural changes in ischemic tissues resulting from the restoration of blood flow to the tissue (reperfusion), including swelling; hemorrhage; necrosis; and damage from free radicals. "The expression of HSPA8 was efficiently enhanced after SCI/R injury, which activated the NF-κB-NLRP3 inflammasome signaling, resulting in spinal ischemia-reperfusion injury." (PMID 35793244, 2022).
lymph node metastasis (1 paper, 2022). "Logistic regression analysis showed that the expression of HSPA8 was closely associated with lymph node metastasis, T stage, and N stage in patients with TNBC." (PMID 36452344, 2022). "In addition, the expression of HSPA8 in TCGA database was considerably correlated with lymph node metastasis, T stage, and N stage." (PMID 36452344, 2022).
lysosomal storage disorders (1 paper, 2021). "HSPA8 may contribute to lysosomal storage disorders (LSDs) as a functional component of lysosome vesicle biogenesis." (PMID 34466782, 2021).
metastatic disease (1 paper, 2021). "HSPA1A and HSPA1B were upregulated, while HSPA8 was downregulated in patients with metastatic disease." (PMID 34765552, 2021).
motor neuron diseases (1 paper, 2023). "The disclosure describes a method for treating motor neuron diseases by administering nucleic acid molecules encoding modulators of the heat shock protein Hsp70, such as mutant Hspa8, with specific characteristics such as missense mutations or altered domains." (PMID 37762045, 2023). "The patent emphasizes the potential relevance of this approach for the treatment of various motor neuron diseases and provides experimental results demonstrating the therapeutic effect of mutant Hspa8 in a model of SMA." (PMID 37762045, 2023).
myocardial ischemia (1 paper, 2019). A disorder of cardiac function caused by insufficient blood flow to the muscle tissue of the heart. "In myocardial ischemia and reperfusion, the myocardial cells release HSPA8 and reduce myocardial cell injury." (PMID 30678657, 2019).
myotilinopathy (1 paper, 2016). "The CASA complex comprises the chaperones HSPB8/Hsp22 and HSPA8/Hsc70, and the co-chaperone BAG3 that were also over-represented in myotilinopathy aggregates." (PMID 26842778, 2016).
ovarian tumor (1 paper, 2024). "The IHC and RT-qPCR results revealed that HSP90AA1 and HSPA8 were downregulated in non-malignant ovarian tumor tissues and significantly upregulated in high-grade serous ovarian cancer samples." (PMID 38166541, 2024). "Furthermore, immunohistochemistry staining (IHC) and real-time quantitative PCR (RT-qPCR) were employed for the validation of the expression and biological functions of core proteins, including HSPAA1, HSPA8, SOD1, and transcription factors SREBF2 and GTAT2, in ovarian tumors." (PMID 38166541, 2024). "RT-qPCR results showed that SOD1 exhibited consistent expression with HSP90AA1 and HSPA8, while SREBF2 and GTAT2 were highly expressed in non-malignant ovarian tumor tissues and significantly decreased in high-grade serous ovarian cancer samples." (PMID 38166541, 2024). "Additionally, the expression levels of HSPA8 and SOD1 were higher in high-grade serous ovarian cancer samples compared to non-malignant ovarian tumor tissues, while RPL13A, PSMA5, and RPSA showed the opposite trend." (PMID 38166541, 2024).
psychosis (1 paper, 2018). "According to a recent study, a polymorphism in the HSPA8 gene (rs1136141) in patients with first-episode psychosis served as a risk factor for psychosis development." (PMID 29514709, 2018).
pulmonary TB (1 paper, 2026). "Upregulated proteins in HSP macrophages included those encoding for Hsp70 family proteins (e.g., HSPA1A, HSPA1B, HSPA6, and HSPA8), which are known to modulate NF-κB–mediated release of pro-inflammatory cytokines from alveolar macrophages in pulmonary TB." (PMID 41489684, 2026).
retinal degeneration (1 paper, 2025). Degeneration of the retina. "Depletion of seven genes (Eif2s1, Hspa5, Hspa8, Nploc4, Hyou1, Ufd1, and Vcp) showed an exacerbating effect on the Rho-Pro23His retinal degeneration compared to the Cas9+/− mice." (PMID 41282224, 2025).
rosacea (1 paper, 2025). A chronic erythematous skin disorder that affects the face. "Notably, proteins commonly implicated in neurodegeneration were increased in rosacea, including α-synuclein (SNCA), HSPA8, and GSK3B, while protein-level pathway enrichment flagged AD- and PD-related pathways." (PMID 41465136, 2025). "In rosacea, proteomic and transcriptomic investigations have revealed enrichment of neurodegeneration-related proteins such as SNCA, GSK3B, and HSPA8, as well as regulatory hubs including PPARG, STAT4, and RORA, which converge on NF-κB, IL-17, and TNF signaling pathways." (PMID 41465136, 2025).
temporal lobe epilepsy (1 paper, 2018). A localization-related (focal) form of epilepsy characterized by recurrent seizures that arise from foci within the temporal lobe, most commonly from its mesial aspect. "Recent study has shown that heat shock cognate 71 kDa protein (Hspa8) is up-regulated in the hippocampus of the lithium–pilocarpine model of temporal lobe epilepsy." (PMID 30274397, 2018).
type 2 diabetes (1 paper, 2023). "It has been revealed that patients with type 2 diabetes exhibit higher levels of the stress-related protein complex HSPA8/Hsp90/CSK2α, along with higher platelet aggregation and thrombogenicity than nondiabetic subjects." (PMID 37569434, 2023).
uterine corpus endometrial carcinoma (1 paper, 2021). A endometrial carcinoma (disease) that involves the body of uterus. "Notably, the mutation of six HSPs, including HSPA4L, TRAP1, HSPH1, HSP90AA1, HSPA8 and HSPA9, was associated with their protein expression in uterine corpus endometrial carcinoma (p < 0.05)." (PMID 34712697, 2021). "For example, the expression of HSPA8 and HSPH1 could be increased and related to good prognosis of patients with their mutations in uterine corpus endometrial carcinoma; HSPA12A mutation in lung adenocarcinoma could down-regulate its expression and lead to poor prognosis." (PMID 34712697, 2021).
cancer (120 papers, 2003 to 2026). A tumor composed of atypical neoplastic, often pleomorphic cells that invade other tissues. "HSPA8 has been implicated in various cancer types due to its involvement in maintaining cellular homeostasis under stress conditions." (PMID 40099939, 2025). "HSPA8 high expression is associated with cancer-related genomic alteration, including up- and downregulation of oncogenes and tumor suppressors, revealing the possible upstream signaling responsible for HSPA8 high expression and downstream networks." (PMID 33926391, 2021). "Considering the importance of cell proteostasis for oncogenesis, an upregulated abundance of HSPA8 is often associated with many cancer types." (PMID 34684727, 2021). "Furthermore, concentrations in HSPA8 levels were associated with cancers, neurodegenerative diseases and ageing, among other conditions." (PMID 33271797, 2020). "In addition, it has been previously reported that HSPA4 and HSPA8 were associated with poor prognosis in cancer." (PMID 32971786, 2020). "In addition, our study revealed that HSPA8 expression might serve as an independent predictor for the OS of CN-AML, and HSPA8 high expression was linked to cancer-related genomic alteration." (PMID 33926391, 2021). "The overexpression of HSPA8 is associated with various disease phenotypes, and downregulating its activity stands as a rational way to influence the course of chronic and acute diseases, as for instance, in cancer, viral infections and neurodegenerative diseases." (PMID 31394830, 2019). "ALO suppresses autophagic flux, disrupts lysosomal homeostasis, and induces lysosomal vacuolation in cancer cells by inhibiting the function of HSPA8, impairing chaperone-mediated autophagy (CMA)-mediated ATP6V1A degradation." (PMID 42318659, 2026). "The discovery of circHSPA8 adds a new dimension to our understanding of HSPA8's function in cancer biology." (PMID 40099939, 2025). "HSPA8 was found to be overexpressed in various cancer cells, which was essential for the growth of cancer cells." (PMID 38395908, 2024). "HSPA8 is frequently overexpressed in human cancers and promotes cancer development and progression in a context-dependent manner." (PMID 39047638, 2024). "High levels of HSPA8 expression have been detected in various cancer cells and are thought to promote cancer cell proliferation and autophagy." (PMID 38419499, 2024). "Of these, HSPA8, HSPA9, PKM, HNRNPA1, NPM1, ANXA2 are already reported to be associated with LN metastasis in GBC or other cancers." (PMID 37142981, 2023). "High expression of HSPA8 has been identified in various cancer cells and is involved in the growth and autophagy regulation of cancer cells." (PMID 37968618, 2023). "These evidences suggest an important function of HSPA8 in the development of diseases, including cancer." (PMID 37771276, 2023). "First, the HSPA8 expression levels in different kinds of cancers were examined using independent datasets from different platforms (TIMER2.0 and ONCOMINE)." (PMID 36452344, 2022). "In previous studies, HSPA8 and RAP1A have been demonstrated to be associated with cancer growth and proliferation in various human cancers." (PMID 35193578, 2022). "And it has been found that low expression of HSPA8 can inhibit the growth of cancer and stop cell proliferation." (PMID 36452344, 2022). "For example, studies have detected HSPA8 in cancer and paracancerous tissues of patients with the same BC and found higher expression in cancer tissues." (PMID 36452344, 2022). "According to related studies, it has been found that HSPA8 is related to metabolic diseases, cancer, aging, and others." (PMID 36452344, 2022). "Udono and Srivastava's studies have reported that HSPA8 in cancer cells binds to tumor-specific antigen peptides in order to facilitate host immune system recognition of them." (PMID 36452344, 2022).
cancer (continued). "HSPA8 overexpression has been found in a wide range of human cancers and is considered to be closely related to tumor invasion and metastasis (Xiang, You & Li, 2018)." (PMID 35186475, 2022). "HSPA8 is overexpressed in a variety of malignant tumor cells, which plays an important role in the occurrence and development of cancer cells." (PMID 36452344, 2022). "Then, the HSPA8 expression level in pan-cancer was evaluated by the ONCOMINE database, which revealed the same result." (PMID 36452344, 2022). "Some overlapped molecules, such as HSPA8 and GAPDH, were found to be regulated by acetylation and deacetylation and associated with invasiveness of cancers." (PMID 34712204, 2021). "HSPA8 has been found overexpressed in various cancer cells, which was indispensable to the growth of cancer cells." (PMID 33926391, 2021). "The HSPA8 protein integrates compensatory mechanisms to drive cellular growth and is dysregulated in multiple chronic stress diseases, including cancer." (PMID 34178637, 2021). "A recent study in multiple human cancers proposed HSPA8 as potential exome markers for cancer detection." (PMID 33670375, 2021). "HSPA8 was associated with most of glycolytic genes like PGK1 (r = 0.21~0.79) and PGAM1(r = 0.17~0.80) across all cancer types (p < 0.05)." (PMID 32635458, 2020). "In summary, we emphasize the findings on the inhibitory effect of OC on HSPA8 in cancer cells under heat shock stress, by inhibiting the translocation of HSPA8." (PMID 33390942, 2020). "In summary, the present study provides evidence that the natural compound OC potentially binds to HSPA8 and Cath B proteins, subsequently suppressing their functions in cancer cells." (PMID 33390942, 2020). "The highest glycolysis score, PGK1 and PGAM1 mRNA abundance were observed under high hypoxia and high HSPA8 expression across cancer types." (PMID 32635458, 2020). "As expected, OC potentially bound to multiple proteins in cancer cells, including HSPA8 and Cath B, which partially explains the complicated MOA of OC in several important signaling pathways, such as autophagy and apoptosis." (PMID 33390942, 2020). "This study highlights the inhibitory effect of OC on HSPA8 in cancer cells under heat shock stress, by specifically inhibiting the translocation of HSPA8." (PMID 33390942, 2020). "P4HA1 was up regulated in cancer cells cultured with hypoxia across all single datasets (p < 0.05), however, HSPA8 was showed the opposite trend in the same conditions in five datasets (p < 0.05)." (PMID 32635458, 2020). "The same distribution as P4HA1, HSPA8 was also proved to be a factor influencing glycolysis score and key glycolysis genes expression in different hypoxia state across cancer types." (PMID 32635458, 2020). "Given that both pharmacological pan-HSPA inhibition and dual knockdown of HSPA8 and HSPA1 caused a strong anti-proliferative response in cancer cells, such a scenario seems possible." (PMID 32987811, 2020). "Another studies demonstrated that only simultaneous depletion of HSPA1 and HSPA8 can effectively block cancer cell proliferation." (PMID 31591429, 2019). "Studies have validated the ability of extracellular HSPA8 to regulate cancer cell proliferation and sperm storage." (PMID 31394830, 2019). "Among HSP70 family, five members have been especially well examined in association with cancer, which are stress-inducible HSP70s, HSP72 (HSPA1) and HSP70B (HSPA6), and constitutively expressed HSP70s, HSC70 (HSPA8), GRP75/Mortalin (HSPA9), and GRP78 (HSPA5)." (PMID 31878360, 2019). "The HSP70s family, including stress inducible member HSP70 (HSPA1A/HSPA1B) and constitutively expressed member HSC70 (HSPA8), plays important roles for protein maturation and correct folding in cancer cell signal transduction and regulation." (PMID 30446660, 2018).